TRPM7 (transient receptor potential cation channel subfamily M member 7)
Diseases named in the same sentence as TRPM7 in open-access papers (continued):
Sharing a sentence is not in itself a finding about the gene and the disease.
cancer (continued). "Interestingly, among the genes that are regulated by TRPM7, SOX2, CD133 and KLF4 are cancer stemness markers." (PMID 30477473, 2018). "In addition to SOCE channels, several TRP channels contribute to the migration of cancer cells, including TRP channels TRPC1, TRPM7, TRPM8, TRPV1, TRPV2, and TRPV6." (PMID 26496025, 2015). "The inhibitory activity on cancer cell growth and proliferation, combined with the TRPM-dependent mechanism, reveals the anticancer potential of midazolam as a TRPM7 inhibitor and supports the suggestion that TRPM7 is a valuable target for pharmaceutical intervention." (PMID 23426784, 2013). "However, the interaction between Annexin-1 and TRPM7 has not yet been demonstrated in cancer cells, nor in preclinical models." (PMID 41395111, 2025). "Furthermore, the methylation of TRPM7 showed a negative correlation with lymph node metastasis, disease recurrence and ultimately cancer-induced mortality." (PMID 40078961, 2025). "Consequently, we asked whether a combined pharmacological inhibition of TRPM7 and HER2 could improve the treatment of HER2-positive cancer cells." (PMID 39513908, 2024). "Chemical inhibitors of the TRPM7 channel inhibit proliferation, growth, migration, invasion, invadosome formation (highly complex molecular structures that facilitate extracellular matrix remodeling and invasion), and markers of EMT in cancer cells, showing potential for future treatment targets." (PMID 37445615, 2023). "TRPM7 regulates a nonselective cation channel and promotes cancer proliferation and metastasis." (PMID 34901284, 2021). "Together, our results indicate that TRPM7 regulates cellular levels of MDMX in part by modulating intracellular zinc concentration, which in turn may provide a new therapeutic target for combinational cancer treatment." (PMID 34627839, 2021). "TRPM7 regulates a nonselective cation channel and enhances cancer metastasis." (PMID 34901284, 2021). "Intriguingly, Trpm7 which is transcriptionally increased in the two Memo1 KO mouse models presented here, is needed for EGF-induced cancer cell migration, a function apparently opposite to Memo1’s role in cancer cell motility, where MEMO1 expression is upregulated." (PMID 32706793, 2020). "Furthermore, TRPM7 has recently been identified as a regulator of SOCE, despite not being a store-operated channel itself, with implications for crosstalk between TRPM7 channels and SOCE in cancer." (PMID 32825277, 2020). "However, the role of TRPM7 in cancer cell resistance has never been studied, even if its expression is clearly linked to cancer progression and reduced survival in breast and pancreatic cancer patients." (PMID 30884858, 2019). "There has yet to be any studies investigating the direct binding of TRPM7 and EGFR in cancer cells, nor is there any evidence of TRPM7 interacting with ANOs." (PMID 36497413, 2022). "In the human neuroblastoma cell line SHEP-21N, the expression of N-myc oncogene correlated with TRPM7 but not with TRPM6 mRNA expression, probably due to the few numbers of malignant tumors with significant TRPM6 expression." (PMID 36844925, 2022).
tumor (94 papers, 2012 to 2025). "It is well-documented that genetic or pharmacological inactivation of TRPM7 causes an inhibitory effect on the growth of tumor cells." (PMID 39513908, 2024). "TRP channels, including TRPC6 and TRPM7, have been implicated in a variety of cellular processes that promote tumor growth, survival, and metastasis." (PMID 39768254, 2024). "Of note, CRTC2-CA or CREB-CA normalized TRPM7 deficiency-induced defects in tumor growth, glucose consumption, as well as SLC2A3 expression." (PMID 36878949, 2023). "Our data have validated that TRPM7 deficiency reduces tumor and EC glycolytic metabolism by inactivating the CRTC2/CREB axis." (PMID 36878949, 2023). "TRPM7 is implicated in neuronal and cardiovascular disorders, tumor progression and has emerged as a new drug target." (PMID 37156763, 2023). "Our results showed a statistically significant association between TRPM7 overexpression and higher tumour grade, metastasis and higher Ki‐67." (PMID 33617107, 2021). "TRPM7 expression was also associated with tumor infiltration, tumor grade, and the presence of distant metastasis." (PMID 33450887, 2021). "Taken together with previous studies, these findings support that upregulation of TRPM7 ion channels is associated with tumor progression and aggressive biological behaviour in GC." (PMID 34938330, 2021). "More specifically, TRPM7 expression can be associated with a decreased production of miR-28-5p, a tumor suppressor inhibiting the expression of oncogenic signaling pathways involving protein-kinase B (AKT), ERK, and IGF-1." (PMID 33928077, 2021). "TRPM7 emerged as a new therapeutic target because malfunctions of TRPM7 have been associated with anoxic neuronal death, tissue fibrosis, tumour progression, and giant platelet disorder." (PMID 32977698, 2020). "TRPM7 is highly expressed in both glioblastoma and pancreatic adenocarcinoma, and has been reported to be associated with tumor migration and invasion." (PMID 32907556, 2020). "This is opposed to a vast body of literature indicating that in several other cell types TRPM7 expression is positively associated with proliferation and migration, in particular in tumor cells." (PMID 29912157, 2018). "We noticed significantly decreased tumor size and weight triggered by TRPM7 deficiency comparing with the control group (T24 LV-NC)." (PMID 27662662, 2016). "TRPM7 is associated with anoxic neuronal death, cardiac fibrosis and tumor progression highlighting TRPM7 as a new drug target." (PMID 25437439, 2014). "TRPM7 was implicated in the invasiveness and dissemination of tumor cells." (PMID 38255793, 2024). "In addition, we try to associate TRPM7 with tumor stage and metastasis to convince high expression was associated with HNSCC invasiveness." (PMID 35771152, 2022). "Here, we reported that TRPM7 silencing changed the transcriptomes involved in modulating cell cycle and acute inflammation, which were linked to tumor cell proliferation and modulated the tumor environment." (PMID 35101076, 2022). "Moreover, TRPM7 expression was significantly associated with tumour malignancy (P = .027), Ki‐67 index (P < .0001) and metastasis (P < .0001)." (PMID 33617107, 2021). "Furthermore, we demonstrated that TRPM7 overexpression is positively associated with prognostic factors such as tumour grade, Ki‐67 index and metastasis." (PMID 33617107, 2021). "Since dedifferentiation status of cancerous tissue is linked to the aggressiveness of tumor growth, therapeutic intervention targeting TRPM7 may have significant impact on highly malignant tumors." (PMID 28810912, 2017). "Also the transient receptor potential melastatin 7 (TRPM7), a Ca2+- and Mg2+-permeant ion channel expressed in T cells, has been implicated in the migration of fibroblasts and tumor cells." (PMID 22952790, 2012). "It suppresses tumor proliferation through mechanisms involving the TRPM7 channel and PPM1D phosphatase, while inducing apoptosis via modulation of the AKT/mTOR and Bax pathways." (PMID 41367628, 2025).
tumor (continued). "And the expression of TRPM7 and TRPM8 exhibited significant associations with the tumour Ki67 proliferation index, tumour size, and Scarff-Bloom-Richardson (SBR) grade." (PMID 40078961, 2025). "In this scenario, one of the most recent investigations, which emphasize the role of TRPM7 in tumor metabolic pathway was conducted by Wu et its collaborators." (PMID 40813985, 2025). "Beyond intrinsic tumor cell regulation, TRPM7 also shapes the TME: it mediates Mg2+ influx into macrophages, driving M2 polarization and thereby accelerating tumor progression." (PMID 41155636, 2025). "TRPM7, a unique bifunctional protein combining ion channel and kinase activities, exerts pleiotropic effects on tumor initiation, progression, and metastasis." (PMID 41155636, 2025). "Mg2+ dependent inhibition of TRPM7 significantly reduced tumor invasiveness, expanding the mechanism of regulation through ROS balance-Mg2+ alleviated oxidative damage." (PMID 41367628, 2025). "BDKRB2 can promote angiogenesis by increasing vascular permeability and upregulating vascular endothelial growth factor (VEGF) and can also promote tumor cell migration and invasion through TRPM7, MMP2, endothelin-1, and ERK signaling pathways." (PMID 40224547, 2025). "Increased TRPM7 expression correlated with a reduced survival rate of tumor patients and more aggressive tumor phenotype." (PMID 38255793, 2024). "The further induction of apoptosis, cell cycle arrest, and increased ROS by TRPM7-mediated restriction of autophagy prevents tumor development and metastasis." (PMID 39633507, 2024). "The activity of the TRPM7 channel is involved in cell proliferation and tumor growth by regulating calcium concentration, while its calcium flux plays a role in modulating cellular resistance to external pressure and epithelial-mesenchymal transition (EMT)." (PMID 39027429, 2024). "The pharmacological inhibitors of TRPM7 have been shown to suppress the proliferation of tumor cells, highlighting TRPM7 as a new anticancer drug target." (PMID 39513908, 2024). "Silencing TRPM7 can inhibit multiple oncogenic signaling pathways and reduce the migration, invasion, colony formation, and tumor sphere formation of human squamous cell carcinoma cells in culture." (PMID 39759147, 2024). "Tumor proliferation regulated by TRPM7 was accompanied by the persistent activation of the JAK2/STAT3 signaling pathway." (PMID 38255793, 2024). "Numerous studies demonstrate the role of TRPM7 chanzyme in tumorigenesis and in other tumor hallmarks such as proliferation, migration, invasion and metastasis." (PMID 38255793, 2024). "Multiple studies indicate that TRPM7 is involved in tumorigenesis and various tumor characteristics, including proliferation, migration, invasion, and metastasis." (PMID 39759147, 2024). "Remarkably, expression was lower in cells resistant to doxorubicin compared with doxorubicin-sensitive tumor cells, and TRPM7 was proposed to be involved in modulating drug resistance." (PMID 38255793, 2024). "Here, we provided detailed descriptions of the role of TRPM7 in numerous tumor types of various organs and tissues, including expression profiles, tumor hallmarks and intracellular signaling pathways in an easy and quick-to-understand way with 10 tables." (PMID 38255793, 2024). "EGF was shown to increase TRPM7 expression and function, and TRPM7 was suggested to be critically involved in the EGF-induced migration of tumor cells." (PMID 38255793, 2024). "This review summarizes the current understanding of the role of transient receptor potential melastatin-subfamily member 7 (TRPM7) channels in the pathophysiology of neoplastic diseases." (PMID 38255793, 2024). "TRPM7 has been proposed to be critical in the migratory and invasive activity of tumor cells and metastasis." (PMID 38255793, 2024). "In pancreatic cancer, TRPM7 correlates with tumor size and stage and its overexpression is characteristic of metastasis." (PMID 36837670, 2023).
tumor (continued). "Very recently, inhibition of TRPM7 by carvacrol in a xenograft GBM mouse model led to reduced tumor size in mice injected with U87MG and U251 cells." (PMID 36768856, 2023). "Using human or mouse-derived healthy and tumor cells, we uncovered that TRPM7 regulates SLC2A3 in a conserved manner." (PMID 36878949, 2023). "Overexpression of TRPM7 decreases the tumor suppressive effects of miR-543 and miR-192-5p in CCa cells." (PMID 37375748, 2023). "Together, our data suggest that TRPM7 controls glucose uptake and utilization to boost tumor growth." (PMID 36878949, 2023). "Higher TRPM7 mRNA and protein expression is connected with bladder cancer and correlates with tumor recurrence, migration, invasion, metastasis, and a poorer prognosis." (PMID 36837670, 2023). "Several studies have demonstrated the implication of TRPM7 in tumor cell proliferation, migration, and poor prognosis, and its aberrant expression in pancreatic and prostate cancer, and leukemia." (PMID 37375748, 2023). "In vivo, TRPM7 activation limited tumor proliferation and metastasis by inducing ROS production, cell cycle arrest, and apoptosis." (PMID 36844925, 2022). "The TRPM7-high and TRPM7-low expression groupings demonstrated substantial differences in tumor differentiation, tumor size, lymphatic node metastatic status, and clinical stage." (PMID 35771152, 2022). "The tumors that developed in mice implanted with TRPM7-silenced cells were markedly smaller at indicated time points compared with the control mice, with a 1.6-fold difference in tumor size by week 8 (p < 0.01)." (PMID 35771152, 2022). "In SAS-injected tumor xenograft mice models, TRPM7 silencing resulted in considerably reduced tumor burden, decreased metastasis, and higher survival rates." (PMID 35771152, 2022). "When compared to their control counterparts, TRPM7-silenced tumor samples had significantly lower expression of NFATC2, Notch1, and P-MEK proteins." (PMID 35771152, 2022). "Expression analysis from the TCGA cohort showed that TRPM7 expression levels increased with tumor stage." (PMID 35771152, 2022). "High expression of TRPM4 and TRPM7 was detected in primary tumor biopsies, while TRPV4, TRPC4, TRPC6 and especially TRPV6 expression was limited, while the expression of TRPC1 and TRPV2 are moderately expressed." (PMID 34936030, 2021). "In HCC, BK-BDKRB2 promotes the migration and invasion of tumor cells through transient receptor potential cation channel subfamily M member 7 (TRPM7) and matrix metalloproteinase-2 (MMP2)." (PMID 33686021, 2021). "In the present study, the effects of TRPM7 expression in tumoral tissues of 204 GC patients on tumor biology and its prognostic significance were investigated." (PMID 34938330, 2021). "Our data suggest that high TRPM7 expression is closely related to progressive tumor behaviour in GC and independently negatively affects survival in patients." (PMID 34938330, 2021). "TRPM7 expression correlates with tumor size, grade, and a high expression of this protein associates with a poor prognosis in patients." (PMID 33450887, 2021). "Although several studies have demonstrated the expression of TPRM7 in MCF‐7 cells or tumour tissues through various experiments, to our knowledge, this is the first study to evaluate TRPM7 expression in CMTs." (PMID 33617107, 2021). "CRC patients with TRPM7 overexpression had deeper tumor infiltration, positive lymph node metastasis, distant metastasis, and advanced clinical stage compared to those with low expression." (PMID 34938330, 2021). "The correlation between TRPM7 expression and clinicopathological parameters (tumour size, histological diagnosis, tumour grade, metastasis and Ki‐67) was assessed." (PMID 33617107, 2021). "Studies have determined that upregulation of TRPM7 is necessary for the proliferation of tumor cells." (PMID 34938330, 2021).
tumor (continued). "TRPM7 overexpression was closely related to high depth of tumor invasion (p < 0.001, ANOVA), increased lymph node metastasis (p < 0.001, ANOVA), and high distant metastasis rate (p < 0.001, Mann-Whitney U)." (PMID 34938330, 2021). "Tumor size was clearly higher in cases with high TRPM7 expression than those with low expression (p < 0.001, Mann-Whitney U)." (PMID 34938330, 2021). "Further experiments with multiple cell models revealed that the anti-tumour effect of NS8593 relies on TRPM7 channel-mediated Mg2+ influx and phosphorylation of RhoA by TRPM7 kinase." (PMID 32977698, 2020). "In our study, we proved that TRPM7 mediates tumor growth, which is consistent with the findings of previously reports." (PMID 32907556, 2020). "TRPM7 activates downstream targets annexin-1, calpain, and myosin, contributing to tumor cell migration and invasion." (PMID 33381038, 2020). "TRPM7 tumor expression was analyzed by IHC stain, wherein the carvacrol treated group showed significantly down-regulated expression of TRPM7 compared to the other groups." (PMID 32907556, 2020). "In previous studies regarding the function of TRPM7 in BC, the effect of TRPM7 downregulation induced BC cell apoptosis via the ERK1/2 pathway, while overexpressed TRPM7 promoted proliferation, migration, invasion, and tumor growth of BC." (PMID 32907556, 2020). "Pathophysiological implications of TRPM7 are widespread and include anoxic neuronal death, hypertension, neurodegenerative disorders, tissue fibrosis, tumour growth/progression and abnormal immune responses." (PMID 32977698, 2020). "Reduced TRPM7 expression was associated with inhibition of Notch activation (Notch1, JAG1, Hey2, and Survivin), involved in angiogenesis and tumor growth mediated by VEGFR and EGFR." (PMID 30995736, 2019). "TRPM7 silencing increased the levels of E-cadherin, but decreased the levels of N-cadherin, Vimentin and Twist expression in tumor tissues." (PMID 30819230, 2019). "In the GSE62254 dataset, TRPM7 showed a higher expression in tumor stage I, which is in agreement with its better prognosis association." (PMID 31083561, 2019). "This IHC finding was corroborated by western blot analyses showing significantly enhanced TRPM7 protein expression level in lung tumor (T) compared to the adjacent non-tumor (NT) tissues (3.4-fold, p < 0.01)." (PMID 30477473, 2018). "In validation, our clinicopathological analyses showed that a higher TRPM7 expression was positively correlated with the larger tumor size (p = 0.007), positive lymph node metastasis (p = 0.005) and disease grade (p = 0.003)." (PMID 30477473, 2018). "We also demonstrated that TRPM7 expression positively correlated with tumor stage, as we observed a 1.9-fold, 2.4-fold, and 3.6-fold increase in the expression of TRPM7 in stage II, stage III and stage IV, when compared with its expression in stage I." (PMID 30477473, 2018). "We demonstrated and compared TRPM7 expression in the non-tumor lung tissues or bronchial epithelial 16-HBE cell line." (PMID 30477473, 2018). "In neuroblastoma cells TRPM7 modulates the cytoskeletal organization and affects the malignancy of tumor cells by regulating actomyosin dynamics and cell-matrix interactions." (PMID 29772843, 2018). "The signaling mechanisms underlying the biological functions of TRPM7 have been elucidated, and how aberrant expression and activity of TRPM7 contributes to neoplasia has begun to be understood." (PMID 28379203, 2017). "The mRNA expression of NB patient tumor samples (Kocak tumor set) was analyzed for TRPM7 using Affymetrix expression profiling." (PMID 29299124, 2017). "A positive correlation between the expression levels of TRPM7 and the primary tumor size and tumor stages was identified." (PMID 25770184, 2015). "A number of studies have suggested that TRPM7 contributes to tumor progression by enhancing cell proliferation." (PMID 25797249, 2015).